INS (insulin)
Diseases named in the same sentence as INS in open-access papers (continued):
Sharing a sentence is not in itself a finding about the gene and the disease.
Hyperinsulinemia (continued). "At the age of 4 months she was hospitalized because of hypoglycemic seizures, glucose levels were at 1.3 mM with concomitant insulin levels of 26.68 μIU/ml (= 185.3 pM) compatible with congenital hyperinsulinism." (PMID 32143698, 2020). "Subsequent carbohydrate-challenge for 7 days increased blood glucose, insulin and proinsulin levels, indicating conditions of hyperglycemia and hyperinsulinemia." (PMID 30858378, 2019). "In skeletal muscle, FGF21 is expressed in response to insulin stimulation, suggesting that FGF21 is an insulin-regulated myokine and an association between chronic hyperinsulinemia and levels of FGF21 were found in humans." (PMID 31057418, 2019). "The endocytosis and/or recycling process of INSR are slowed down leading to hyperinsulinemia with altered insulin response and insulin clearance." (PMID 31658625, 2019). "IR leads to increased insulin secretion from the pancreas to maintain normal blood glucose levels, resulting in compensated hyperinsulinemia, which in turn stimulates fat storage and affects cholesterol and lipoprotein metabolism." (PMID 31526389, 2019). "The increased glucose-induced hyperinsulinemia observed in Napepld∆IEC mice prompted us to verify insulin sensitivity with an insulin tolerance test." (PMID 30692526, 2019). "Pancreatic β cells increase insulin release to overcome the reduced efficiency in insulin action in order to maintain normal blood glucose levels; however, this is accompanied by a chronic and subclinical hyperinsulinemia." (PMID 31430977, 2019). "Insulin sensitivity is impaired during weight gain by a high-calorie, high-fat (HF) diet, for which hyperinsulinemia can be compensatory." (PMID 30846785, 2019). "Insulin suppressed Bmf and stimulated hnRNP F expression in RPTCs of hyperinsulinemic-euglycemic mice after 3 h of hyperinsulinemia as compared to Akita mice after 4 weeks of insulin implantation." (PMID 31040360, 2019). "Serum fasting insulin ranged between 36 and 294 pmol/L, while fasting hyperinsulinemia (>115 pmol/L based on the used assay) was present in 43 adolescents." (PMID 31634867, 2019). "The obese subjects had significant postprandial hyperinsulinemia compared to the lean group despite similar glycemic response, indicative that they require more insulin to maintain the same glucose tolerance owing to peripheral tissue insulin resistance." (PMID 31068904, 2019). "Inactivation of Ir can induce hyperinsulinemia, reduce insulin clearance and impair carbohydrate homeostasis in liver-specific Ir knockout mice." (PMID 30621263, 2019). "In a prolonged hyperinsulinemia state, accumulation of unrecycled INSR is targeted for degradation, resulting in deficiency in INSR and impaired insulin clearance ability." (PMID 31658625, 2019). "Hyperinsulinemia and blunted insulin responsiveness, measured in this work using fasting C-peptide levels, are commonly associated with impaired glucose tolerance, increased adiposity, and reduced adiponectin levels." (PMID 30728429, 2019). "While the increased levels of circulating insulin is known as hyperinsulinemia and has been proposed as an attempt to compensate for reduced insulin sensitivity." (PMID 31695458, 2019). "Marked hyperinsulinemia (4500 μU/mL) and high titers of insulin antibodies (80.4%) with high binding capacity and low affinity indicated that IAS-like insulin antibodies were causing severe glucose fluctuations." (PMID 30621663, 2019). "During pregnancy, body weight gains too fast and fat accumulates, which continuously stimulates the secretion of insulin from pancreatic islet β-cells and triggers hyperinsulinemia." (PMID 31362999, 2019). "•Valuable for researchers interested in the impact of Ide deletion and insulin dysregulation, specifically hyperinsulinemia, on prediabetes onset." (PMID 31198829, 2019).
Hyperinsulinemia (continued). "In an insulin resistant state, hyperinsulinemia-induced receptor tyrosine kinase activation commonly leads to activation of PI3K/Akt signaling, and thus activates proinflammatory NF-κB in kidney." (PMID 30811347, 2019). "The Zip14 knockout mouse is characterized by hyperinsulinemia, however, with signs of impaired insulin secretion upon high glucose stimulation, as well as impaired hepatic gluconeogenesis and glycolysis." (PMID 31197210, 2019). "IR impacts glucose utilization, resulting in a compensatory increase in beta-cell insulin production and hyperinsulinemia." (PMID 30889804, 2019). "The exaggerated natriuresis over 24 hours resulted from prevention of meal-induced hyperinsulinemia and the postprandial increase in insulin-mediated sodium conservation." (PMID 30862903, 2019). "In intestinal endotoxic conditions, over-secretion of incretin were found to induce insulin secretion and glucose lowering leading to hyperinsulinemia and blood glucose lowering." (PMID 31126070, 2019). "Chronic hyperinsulinemia eventually triggers CNS-IR, thereby reducing the insulin levels in the brain via the BBB, affecting energy homeostasis and cognitive disruption." (PMID 31212845, 2019). "The TIMP1 (TIMP Metallopeptidase Inhibitor 1) gene participates in the inhibition of the insulin signaling mechanism and its product levels were shown to increase as a result of hyperinsulinemia." (PMID 31138121, 2019). "Considering that alcohol, cannabinoid, and HFD exposure can compromise hepatic enzyme function to promote hyperinsulinemia and impair insulin signaling, our findings counter the expectation of increased trunk insulin level in the HFD-fed COM group." (PMID 31427627, 2019). "Iron can also interfere with insulin extraction in the liver, and thereby contribute to peripheral hyperinsulinemia." (PMID 31807124, 2019). "In the present study, LCD and LCD + INT similarly decreased hyperinsulinemia as assessed by insulin iAUC120min." (PMID 31552710, 2019). "This affects the interaction between insulin and its receptor, leadingto decreased glucose uptake by insulin-dependent cells, and ultimatelyhyperglycemia and hyperinsulinemia." (PMID 31188964, 2019). "Our experiments were focused on evaluating the impact of sustained hyperinsulinemia or impaired insulin sensitivity on TPCs." (PMID 31949435, 2019). "Eating small meals and α-glucosidase treatment to decrease insulin secretion are recommended to suppress the hyperinsulinemia." (PMID 30621663, 2019). "The decrease of the CD4/CD8 ratio of T-lymphocytes evoked by short-term hyperinsulinemia in both groups of subjects suggests a marked role of insulin in the balance of these two cell populations." (PMID 30983877, 2019). "Higher blood glucose levels are initially compensated by increased pancreatic insulin secretion (hyperinsulinemia) leading to decreased myocardial insulin sensitivity which then further decreases glucose uptake and oxidation." (PMID 30343468, 2019). "Chinese herbal formula TZQ-F treatment upregulates the expression of related proteins such as GLUT-1, which regulates the potency of insulin action and is beneficial for reducing hyperinsulinemia." (PMID 31258478, 2019). "Insulin-mediated suppression of HGP during physiological hyperinsulinemia was decreased from the basal levels in all groups." (PMID 31853220, 2019). "We demonstrated that SSE supplement abrogated the adverse effects of HFD on insulin sensitivity—responses to insulin load were normalized and hyperinsulinemia was abolished." (PMID 31847157, 2019). "Reductions of insulin sensitivity and compensatory hyperinsulinemia are physiological during puberty, and this partly reflects the effects of increased growth hormone and IGF-1." (PMID 30931082, 2019). "Hyperinsulinemia, strictly related to abdominal obesity, reduces the vasodilatory capacity of insulin, thereby reducing the production of nitric oxide by endothelial cells." (PMID 31277306, 2019).
Hyperinsulinemia (continued). "Upregulation of inflammatory and pro‐oxidative markers in 6‐month‐old Cc1−/− mice was ascribed to hyperinsulinemia due to reduced hepatic insulin clearance." (PMID 31389127, 2019). "Restoration of hyperinsulinemia by subcutaneous insulin infusion abrogated the effects of both dapagliflozin and CRMP to slow tumor growth." (PMID 31867105, 2019). "Currently, the recommended test to diagnose hyperinsulinemia is the dynamic OST to assess the postprandial insulin response." (PMID 31498947, 2019). "The majority of studies found increased plasma insulin levels (i.e., hyperinsulinemia) in the fasting state in DM1 patients, but the percentage of DM1 patients reported to be affected by this was highly variable." (PMID 31849810, 2019). "In fact, hyperinsulinemia in and of itself can be responsible for hyperandrogenism since insulin and Insulin-like growth factor 1 (IGF-1) can act as co-gonadotropins, stimulating ovarian steroid production along with gonadotropins." (PMID 31367382, 2019). "At the same time, insulin is an important modulator of apelin expression and secretion, and high concentrations of apelin are observed in hyperinsulinemia, indicating a correlation between apelin and insulin." (PMID 30696454, 2019). "Obese mice developed hyperinsulinemia, culminating in substantially higher fasting glucose, insulin levels, TG levels, and glucose tolerance, as compared to age-matched controls." (PMID 31246177, 2019). "We proposed that some of the renal sodium retention in the postprandial period is a result of increased ENaC activity stimulated by insulin from glucose-induced hyperinsulinemia following a meal." (PMID 30862903, 2019). "Our findings highlight the need for monitoring insulin levels in PCa patients receiving ADT, who will predictably develop hyperinsulinemia, and build a strong case for targeting insulin and downstream activated pathways." (PMID 31379747, 2019). "The association between the MS and preeclampsia is supported by evidence of increased hyperinsulinemia, abnormal placental accumulation of glycogen and unusual insulin mediators with subsequent impaired placental insulin signaling." (PMID 31622409, 2019). "Hyperinsulinemia persists at this state; however, elevated insulin level is already unable to maintain normal fasting blood glucose level in light of insulin resistance." (PMID 30478982, 2019). "Male and female newborns of mildly hyperglycemic sows exhibited IGT, whereas only females showed fasting hyperinsulinemia and increased insulin secretion." (PMID 31308048, 2019). "Hyperinsulinemia, the presence of excess insulin relative to glucose in the blood, is considered to be a poor prognostic indicator for patients with triple-negative breast cancer (TNBC)." (PMID 31315653, 2019). "Zip14 knockout mice display hyperinsulinemia and impaired insulin secretion in high glucose conditions." (PMID 31197210, 2019). "Acutely GI-inflamed mice showed hyperinsulinemia in a fasting state, and insulin secretion was more elevated than in the control group following glucose administration." (PMID 31126070, 2019). "First, it has been repeatedly reported that serum omentin levels are inversely related with HOMA-IR/fasting insulin and an in vitro study supported the role of hyperinsulinemia in lessening omentin expression in adipose tissue." (PMID 31382403, 2019). "Hyperinsulinemia impairs insulin activity and metabolic signaling pathways and also affects the structure and function of the tissues and organs including the kidney." (PMID 31737684, 2019). "Insulin sensitivity is also related with salt sensitivity by hyperinsulinemia, over-activation of sympathetic nervous system, and reducing suppression of RAAS pathway." (PMID 31565555, 2019). "Two of the DM patients had a delayed insulin response with relative hyperinsulinism (vs. NGT acromegaly and healthy controls) toward the end of IVGTT, similar to non-acromegalic diabetic patients." (PMID 31620090, 2019).
Hyperinsulinemia (continued). "Endogenous hyperinsulinism is an abnormal clinical condition that involves excessive insulin secretion, related in 55% of cases to insulinoma." (PMID 31448019, 2019). "Congenital hyperinsulinism is a rare condition of hypoglycaemia due to dysregulated insulin production from pancreatic beta cells." (PMID 32832699, 2019). "Normal values of urine organic acid, serum amino acid panel, plasma acylcarnitine profile, insulin and C-peptide, allowed to exclude respectively beta oxidation disorders and hyperinsulinism." (PMID 30999961, 2019). "Studying patients with congenital hyperinsulinism and the 9p deletion syndrome provides an opportunity to further unravel the genetic underpinnings of dysregulated insulin secretion in congenital hyperinsulinism." (PMID 32832699, 2019). "Serum leptin and insulin levels were comparable between the 2 cohorts at 8 weeks of age, but thereafter, Sel1LPOMC mice developed hyperleptinemia and hyperinsulinemia." (PMID 29457782, 2018). "It is known that hyperinsulinemia is neurotoxic, and thus it is possible that insulin sensitivity and insulin signaling pathway improvements after exercise would favor neurogenesis, and thereby improved cognitive function." (PMID 29387262, 2018). "Hyperinsulinemia has been known to reduce the vasodilation capacity of insulin by attenuating nitric oxide production by endothelial cells." (PMID 29991967, 2018). "At 36 weeks, fasting plasma insulin was determined and, as anticipated, DIO mice displayed robust hyperinsulinemia, with a 4.7-fold increase in insulin compared to SD mice." (PMID 30446513, 2018). "All our subjects had normal glucose tolerance; however, the obese insulin-resistant subjects had fasting hyperinsulinemia, but significantly lower percentage change in insulin response compared to lean insulin-sensitive subjects." (PMID 29385178, 2018). "Treatment of 3T3-L1 adipocytes with 10 nm insulin for 24 h to mimic hyperinsulinemia or with 2 ng/ml TNFα for 96 h to mimic chronic pro-inflammatory signaling impaired insulin-stimulated 2-deoxyglucose (2DOG) uptake." (PMID 29599292, 2018). "This reduction in food intake is partially attributable to the anorexic effect of insulin and leptin on the hypothalamus, which is upregulated in dexamethasone-treated rats as they develop hyperinsulinemia and hyperleptinemia." (PMID 30532777, 2018). "Adiponectin was 9.51 ± 12.08 μg/mL in those with insulin below the normal range, 5.21 ± 6.24 μg/mL in those whose insulin was within the normal range and 1.43 in the only participant with hyperinsulinemia." (PMID 29890036, 2018). "Subcutaneous injection of insulin is widely accepted in diabetic patients, but it is invasive and thus has many disadvantages such as infections, hypoglycemia, peripheral hyperinsulinemia, and poor pharmacodynamic." (PMID 30524677, 2018). "These animals also maintained normal circulating insulin levels and glucose metabolism till they were 13 months old when there was evidence of plasma hyperinsulinemia." (PMID 29950970, 2018). "Hyperinsulinemia was evident in mice fed a HF diet and circulating levels of insulin were significantly decreased in mice fed a HF diet containing inulin alone or in combination with isoquercetin." (PMID 29973701, 2018). "Conversely, the skeletal muscle-cells of insulin-resistant individuals fail to gain competitive advantages under hyperinsulinemia and dispose of significantly less serum glucose, thereby increasing the availability of glucose to other cell-types." (PMID 30147656, 2018). "During the hyperinsulinemic-euglycemic clamp at 100–220 min, serum insulin concentration was at a steady-state plateau of hyperinsulinemia, but serum insulin concentration differed significantly from the NGT to borderline type and T2DM subjects." (PMID 29560274, 2018). "This is a pathologic state in which target tissues cannot respond to insulin at the physiological level, leading to the development of hyperinsulinemia with euglycemia." (PMID 30233495, 2018).
Hyperinsulinemia (continued). "This early observed hyperinsulinemia, hyperleptinemia and hypoadiponectinemia indicates that the known development of insulin and leptin resistance in adults born with IUGR manifests early in childhood." (PMID 30356143, 2018). "Most T2DM patients have hyperinsulinemia, a condition that defines high insulin levels in the blood." (PMID 29475434, 2018). "Compared with 10 healthy individuals, colectomy individuals had higher peak levels of plasma glucose and higher peak levels and area under the curve of plasma insulin suggesting impaired glucose tolerance and hyperinsulinemia." (PMID 30373718, 2018). "In the present study, the HFD control animals showed a significant increase in serum insulin levels compared to lean control (P<0.01), as a cardinal sign of hyperinsulinemia." (PMID 30524684, 2018). "Insulin-dysregulated horses and ponies can have tissue resistance to the effects of insulin resulting in persistent hyperinsulinemia, but alternatively can simply experience an abnormally large post-prandial insulin response to carbohydrate-rich meals." (PMID 29958298, 2018). "Severe hyperinsulinemia (circulating insulin above 70 μIU/mL) and/or a history of severe laminitis did not occur in within our sample set." (PMID 30001422, 2018). "Gross hyperinsulinemia was confirmed by immunoassay, and low insulin recovery following PEG precipitation suggested IA." (PMID 30085133, 2018). "In this study, we have provided multiple lines of evidence that PRKD2 down-regulation is sufficient to enhance β-cell insulin secretion and subsequently induce hyperinsulinemia and systemic IR." (PMID 29789568, 2018). "Nevertheless, by using euglycemic hyperinsulinemia, we were able to study insulin sensitivity of liver GU, which contributes to glucose clearance after a meal." (PMID 29535167, 2018). "Measurement of plasma insulin showed significant diet-induced hyperinsulinemia (2.4-fold increase) in wild type mice." (PMID 30510203, 2018). "In a state of hyperinsulinemia, insulin increases bio-availability of another class of factors, i.e. insulin-like growth factors (IGF), which are one of the key regulators of energy metabolism and growth." (PMID 29475434, 2018). "Impaired removal of insulin by the injury liver and porto-systemic shunts make hyperinsulinemia in cirrhotic patient." (PMID 29416767, 2018). "First, the hyperinsulinemia was substantially alleviated, as manifested by the dramatic decrease in the serum level of fasting insulin." (PMID 30140027, 2018). "In T2DM, peripheral hyperinsulinemia increases the concentration of insulin which acts as a competitive substrate for IDE and inhibits the degradation of Aβ that gradually accumulates to form insoluble plaques." (PMID 29950970, 2018). "T2DM is often preceded by an insulin resistant state, where the normal biological response to the hormone insulin is impaired and insulin production is disregulated (compensatory hyperinsulinemia) to maintain normoglycemia." (PMID 29899246, 2018). "Hyperinsulinemia increases colon cancer cell resistance to 5-fluorouracil, and oxaliplatin chemotherapy, and exposure to insulin promotes colonic tumor multiplicity." (PMID 30332430, 2018). "Apart from attenuating hyperinsulinemia or metabolic disorders in vivo and thus inhibiting insulin- or metabolite-dependent proliferative effects by both metformin and liraglutide, these two drugs also have direct anti-tumor effects in the in vitro studies." (PMID 29897998, 2018). "On one hand, it is possible that castration rescued insulin sensitivity and β-cell function, eliminating the need for hyperinsulinemia as a compensatory mechanism, thus resulting in a rescued metabolic phenotype." (PMID 29385050, 2018). "For example, under hyperinsulinemia, the skeletal muscle-cells of insulin-sensitive individuals dispose of 70–90% of serum glucose at the expense of other tissues." (PMID 30147656, 2018).